TRBV27 (T cell receptor beta variable 27)
Description:
V region of the variable domain of T cell receptor (TR) beta chain that participates in the antigen recognition. Alpha-beta T cell receptors are antigen specific receptors which are essential to the immune response and are present on the cell surface of T lymphocytes. Recognize peptide-major histocompatibility (MH) (pMH) complexes that are displayed by antigen presenting cells (APC), a prerequisite for efficient T cell adaptive immunity against pathogens. Binding of alpha-beta TR to pMH complex initiates TR-CD3 clustering on the cell surface and intracellular activation of LCK that phosphorylates the ITAM motifs of CD3G, CD3D, CD3E and CD247 enabling the recruitment of ZAP70. In turn ZAP70 phosphorylates LAT, which recruits numerous signaling molecules to form the LAT signalosome. The LAT signalosome propagates signal branching to three major signaling pathways, the calcium, the mitogen-activated protein kinase (MAPK) kinase and the nuclear factor NF-kappa-B (NF-kB) pathways, leading to the mobilization of transcription factors that are critical for gene expression and essential for T cell growth and differentiation. The T cell repertoire is generated in the thymus, by V-(D)-J rearrangement. This repertoire is then shaped by intrathymic selection events to generate a peripheral T cell pool of self-MH restricted, non-autoaggressive T cells. Post-thymic interaction of alpha-beta TR with the pMH complexes shapes TR structural and functional avidity.
Synonyms: TCRBV14S1; TCRBV27S1
Gene: T-cell receptor variable (V) gene on chromosome 7 (142,715,346 to 142,715,861, forward strand). Ensembl gene ENSG00000211752.
Subcellular location: Cell membrane
Gene Ontology:
Biological process: cell surface receptor signaling pathway
Cellular component: plasma membrane
Homologues: Orthologues: macaque TRBV27 (93% identical), pig TRBV27 (69% identical). Paralogues in human: TRBV10-2 (59% identical), TRBV28 (58% identical), TRBV6-7 (57% identical), TRBV6-1 (56% identical), TRBV6-2 (56% identical), TRBV6-5 (56% identical), TRBV6-8 (55% identical), TRBV10-1 (54% identical), TRBV10-3 (54% identical), TRBV6-6 (54% identical), TRBV19 (53% identical), TRBV24-1 (52% identical), and 39 more.
Diseases named in the same sentence as TRBV27 in open-access papers:
TRBV27 is named in the same sentence as 8 diseases in open-access papers, as found by Europe PMC text mining. Sharing a sentence is not in itself a finding about the gene and the disease. The quoted sentences say what the papers report.
melanoma (1 paper, 2009). A malignant, usually aggressive tumor composed of atypical, neoplastic melanocytes. "Conversely, other authors reported that the recognition of melanoma Ags involved the use of T lymphocytes bearing specific TRBV chains, such TRBV5, TRBV9, TRBV19, TRBV27, and TRBV28." (PMID 19317896, 2009).
bacterial infection (1 paper, 2023). "PRP also upregulated the genes involved in the beta chain of the T cell receptor (TRBV3‐1, TRBV6‐5, TRBV7‐2, TRBV27, TRBC2, and TRBJ2‐3), which is responsible for antigen recognition and activation of cellular immunity during bacterial infection." (PMID 36704119, 2023).
infection (1 paper, 2025). The state of being infected such as from the introduction of a foreign agent such as serum, vaccine, antigenic substance or organism. "In line with this, the usage of the V and J genes was very similar during the course of infection, in which mainly genes from the TRBV28, TRBV27, and TRBV6 families, as well as the TRBJ1-01 gene, were detected." (PMID 40573882, 2025).
TRBV27 also shares sentences with these, for which no sentence is quoted: cancer (1 paper); COVID-19 (1); Graves disease (1); Hashimoto thyroiditis (1); tumor (1).